IL4 (interleukin 4)
Diseases named in the same sentence as IL4 in open-access papers (continued):
Sharing a sentence is not in itself a finding about the gene and the disease.
allergic asthma (continued). "Th2 and Th17 cells and their hallmark cytokines, i.e., IL-4 and IL-17, respectively, play crucial roles in the pathogenesis of allergic asthma." (PMID 34071080, 2021). "The expressed proteins of IL-4 activated alveolar macrophages perform diverse functions in allergic asthma, ranging between protective and pathogenic roles." (PMID 32024540, 2020). "Allergic asthma is caused by immediate hypersensitivity reaction (type I), which is initiated by antigen exposure, activating specific Th2 cells that produce IL-4, IL-5 and IL-13." (PMID 32024540, 2020). "It is also associated with interleukin- 4 and interleukin- 13, but these cytokines are crucially important in allergic asthma cases." (PMID 31885750, 2019). "T helper type 2-associated cytokines IL-4, IL-5 and IL-13 are involved in the pathogenesis of the eosinophilic airway diseases such as allergic asthma, allergic rhinitis and NP." (PMID 30519393, 2018). "The presence of high serum titers of atopy IgE in serum is the hallmark of allergic asthma immunity.Th2 cell effector cytokine IL-4 contributes to plasma class switching of the immunoglobulins in B cells." (PMID 28724400, 2017). "Allergic asthma is a T helper 2 cell (Th2)-mediated disease, in which Th2 cytokines interleukin (IL)-4, IL-5, and IL-13 are closely associated with the symptoms." (PMID 26965110, 2016). "Batf deficiency impairs the generation of IL-4-producing Tfh cells that results in protection against allergic asthma." (PMID 26278622, 2015). "Down-regulation of TLR3 expression using siRNAs in rats caused a decrease of serum IgE levels and a reduction of IL4 mRNA expression in immune organs in an allergic asthma model." (PMID 23882263, 2013). "Th2 type cytokines such as IL-4, IL-5 and chemokines have been implicated in the pathology of allergic asthma." (PMID 19657391, 2009). "In addition, LincR-PPP2R5C deficiency impaired IL-4 production in a murine model of allergic asthma." (PMID 39287443, 2024). "IL-6 was reported to promote IL-4 production during Th2 cell differentiation and inhibit Th1 differentiation, which caused IL-6 to be highlighted as a major potential contributor of the allergic asthma pathology." (PMID 37998734, 2023). "In humans, an allergic asthma response is often associated with a systemic increase of IL-4 and IL-5, both of which have been linked to an increased likelihood of birthing a child later diagnosed with neurodevelopmental disorders when higher levels occur during pregnancy." (PMID 36009104, 2022). "Although there are different disease phenotypes, the hallmark of allergic asthma is a type 2 immune response, characterized by IL-4, IL-5, and IL-13 secretion by T helper 2 (Th2) lymphocytes, IgE secretion, recruitment and activation of eosinophils, mast cells, dendritic cells and epithelial cells." (PMID 34834178, 2021). "In allergic asthma, Cloots and coworkers showed that mice genetically deficient for Arg1 displayed a reduction in Il4, Il5, Il13, Ccl2, and Ccl11, all Th2-related genes, suggesting that Arg1 may regulate type 2 inflammation." (PMID 34834178, 2021). "Our study suggests that Sema3E could be considered as a novel treatment for chronic allergic asthma via regulation of both Th2, e.g. IL-4 and IL-5, and Th17, e.g. IL-17A, associated cytokines." (PMID 29228740, 2017). "Like IL-4, IL-9 is associated with type II immune responses, such as in allergic asthma." (PMID 26936133, 2016). "The results showed that the expression levels of TSLP, IL-33, IL-4, IL-5, and IL-13 were higher in clusterB or gene clusterB than those in clusterA or gene clusterA, which suggested that clusterB or gene clusterB is highly linked to allergic asthma characterized by the Th2 immune response." (PMID 33763115, 2021). "The levels of IL-4 were also slightly higher in sarcoidosis patients than in non-allergic asthma (p = 0.02) and amiodarone lung (p = 0.01) patients." (PMID 40725075, 2025).
allergic asthma (continued). "This influx of ILC2 cells combined with the production of IL‐4, IL‐5 and IL‐13 from these Th2‐like Tregs worsens allergic asthma and food allergy." (PMID 40497455, 2025). "Administration of three doses of a neutralizing anti-IL4 antibody during the challenge phase reduces the aggravated allergic asthma symptoms of KSRP−/− mice to the level of OVA-challenged WT animals." (PMID 40095032, 2025). "Specifically, SCFAs enhance regulatory T cell development, suppress allergic inflammation, and reduce Th2-type cytokine production, including IL-4, IL-5, and IL-13, in allergic asthma." (PMID 40529126, 2025). "Our study demonstrates that FOR811A, a nitric oxide donor, was able to reduce the IL-4 levels in an allergic asthma model." (PMID 40136501, 2025). "Allergic asthma, which is common in childhood, exhibits a T2-high response with activation of IL-4, IL-5, IL-9, or IL-13, accompanied by eosinophilic inflammation." (PMID 40867700, 2025). "Allergic asthma is typically characterized by high expression of IL-4, IL-5, and IL-13, along with elevated IgE levels and eosinophil infiltration; it is a prototypical type 2 inflammation-driven disease." (PMID 40430465, 2025). "Second, these monocytes demonstrated a greater capacity to adopt a more potent M2 macrophage phenotype in response to IL-4 polarization, a factor that is crucial for responsiveness to allergic asthma." (PMID 40034689, 2025). "In the BAL of patients with non-allergic asthma, we measured decreased concentrations of IL-4, IL-8, IL-13, IFN-γ, C4a, C5a, and MCP-1 and increased concentrations of IL-6, IL-12p70, TNF-α, and C3a." (PMID 40725075, 2025). "Clinical studies in children with allergic asthma have shown that HDM-AIT increased methylation in the Il4 gene promoter and reduced IL-4 production by PBMCs compared with those in untreated children." (PMID 41145900, 2025). "The immune response to allergic asthma is primarily regulated by Th2 lymphocytes, which release IL-4, IL-5, and IL-13." (PMID 39858200, 2025). "Many biologics have been developed to combat type 2 inflammation and allergic asthma, with IL-4Rα being one of the main targets, since both IL-13 and IL-4 utilize it as a receptor." (PMID 40170850, 2025). "Formononetin and astragaloside IV, active constituents of Astragalus mongholicus, have been shown to suppress Th2 cytokines such as IL-4 and reduce eosinophilic infiltration in allergic asthma models." (PMID 40429990, 2025). "HDM is known to trigger the release of allergic asthma related cytokines, namely IL-4, IL-5 and IL-13 from Th2 cells, innate immune cells and innate lymphoid cells thereby driving eosinophil-predominant airway inflammation." (PMID 39129025, 2024). "CycloZ bridges this gap by dual mechanisms: it mitigates TLR4-driven immune triggers of allergic asthma and reduces downstream Th2-mediated inflammation, notably decreasing cytokines like IL-4 and IL-13." (PMID 39682780, 2024). "At 30 days post-OVA administration, allergic asthma mice exhibited increased levels of IgE and IL-4 in serum and lung tissue, higher pathological scores, and elevated eosinophils in bronchoalveolar lavage fluid (BALF) compared to control mice." (PMID 39484217, 2024). "First, Th2 cells produce IL-4, IL-5, and IL-13, which promote allergic asthma, and higher Se intake skews differentiation toward Th1/Treg and away from Th2 phenotypes." (PMID 38826577, 2024). "It has been shown that Th2 cytokines of IL-13, Il-4, and IL-5 are deeply involved in the early phase of allergic asthma pathogenesis." (PMID 39062810, 2024). "Another major feature of the airway inflammation induced in allergic asthma is a type 2 immune response that involves the release of various cytokines, including IL-4, IL-5, and IL-13." (PMID 38790633, 2024).
allergic asthma (continued). "Considering the restrictions of prevailing therapies, we have identified the novel feature of DMF in combating allergic asthma by reducing the production of pro-inflammatory cytokines, i.e., IL4, IL13, and IL17, in the bronchoalveolar tissue." (PMID 38711519, 2024). "CCR4 is expressed by type‐2 inflammatory cells, including Th2 cells and innate lymphoid cells, which generate IL‐4, IL‐5, and IL‐13, and contribute to the etiology of allergic asthma." (PMID 39508721, 2024). "In this research, our emphasis was on Th2 cell differentiation, giventhe importance of this subset in allergic asthma due to the secretionof IL-4, IL-5, and IL-13." (PMID 38144091, 2023). "Allergic asthma is a respiratory disease initiated by type-2 immune responses characterized by secretion of alarmins, interleukin-4 (IL-4), IL-5, and IL-13, eosinophilic inflammation, and airway hyperresponsiveness (AHR)." (PMID 36865540, 2023). "Allergic asthma has been generally considered a Th2 cell-mediated chronic immune response, while Th2 cells produce effector cytokines such as IL-4 and IL-13 to mediate respiratory symptoms." (PMID 37957139, 2023). "In a mouse model of experimental allergic asthma, local application of recombinant IL-37 lowered the secretion of IL-4, IL-5, and IL-13, thereby reducing Th2-mediated allergic airway inflammation." (PMID 38067193, 2023). "Geraniol is reported to ameliorate allergic asthma by reducing eosinophils, Th2 cytokines like IL-4, 5 and 3 and increasing Th1 cytokine like interferon γ, Nrf2 protein expression, and reduced glutathione." (PMID 37251328, 2023). "The early sensitization phase of allergic asthma is characterized by DC-induced Th2 cells that produce IL-4 and promote B-cell switching toward allergen-specific IgE-secreting cells." (PMID 37346413, 2023). "Results from our study support the possible role of Nr1d1/2 (reduced mRNA expression) in chronic HDM-induced allergic asthma with heightened il4, il5, and il13 expression at ZT12." (PMID 37664635, 2023). "On the other hand, the formation of Th2 lymphocytes from IL-4-producing Tfh lymphocytes was shown in allergic asthma in vivo." (PMID 38022605, 2023). "Compared to the results for the normal group, in the model group, the serum IFN-γ levels were distinctly lower (P < 0.01) and the expression of IL-4 and IgE was higher (P < 0.01), indicating that an imbalance in the Th1/Th2 ratio in allergic asthma rats." (PMID 36717898, 2023). "Th2 cells contribute to the pathogenesis of allergic asthma by producing Th2 cytokines, such as IL-4, IL-5, and IL-13, leading to eosinophil accumulation in the airway wall, mucus overproduction, and IgE synthesis." (PMID 36077141, 2022). "In summary, our findings showed that maternal high-fat diet during pregnancy promoted the proliferation and effector function of TH2-cells via the hypomethylation of Il-4 promoter region to trigger allergic asthma in offspring." (PMID 35745240, 2022). "IL-4 and IL-5 along with other Th2-cytokines are involved in the airway inflammation observed in the lungs of patients with allergic asthma." (PMID 35547729, 2022). "IL-5 plays a key role in the differentiation, maturation, chemotaxis and activation of eosinophils and often cooperates with IL-4 to upregulate the level of eosinophils in patients with allergic asthma." (PMID 35744915, 2022). "Th2 cytokines, including IL‐4, IL‐5, and IL‐13, are important factors in the pathophysiological characteristics of allergic asthma." (PMID 35344278, 2022). "Th2 cells secreting IL–4, IL–5, and IL–13 play a key role in the inflammatory process in allergic asthma, smooth muscle spasms, and mucus production." (PMID 36558973, 2022). "While on the other hand, Th2 cytokines such as IL-4/IL-13 can also promote the proliferation and expansion of pulmonary ILC2s in allergic asthma." (PMID 35281601, 2022).
allergic asthma (continued). "Studies showed that IL4, a key effector Th2 cytokine in allergic asthma, was essential for B cells autophagy induction in vivo and in vitro, thereby further sustaining B cell survival and enhanced B cell antigen presentation." (PMID 35600600, 2022). "Here, we showed that our model of MAA recapitulates the exposure to cytokines that are hallmarks of the allergic asthma response, including increased levels of IL-4, IL-6, IL-5, IL-13, and IL-17." (PMID 36009104, 2022). "Overall, our results suggest that dual IL-4/IL-13 vaccination is a promising long-term therapeutic strategy for allergic asthma, pending further safety and feasibility assessment in additional preclinical models." (PMID 33976140, 2021). "Airway inflammation, mucus hypersecretion, and airway hyperresponsiveness (AHR) are the major symptoms of allergic asthma and are profoundly impacted by Th2 cytokines, such as IL-4, IL-5, and IL-13, and chemokines." (PMID 33919784, 2021). "The activated T lymphocytes then produce several pro-inflammatory cytokines such as interleukin (IL) IL-4, IL-5, IL-9, IL-13, and GM-CSF that are major components of the inflammatory response in AR as well as allergic asthma." (PMID 34638811, 2021). "Th2-mediated allergic responses to fungal in mice, resulting in repeated lung exposure to fungal strains, produce IL-4 and IL-13 as well as the intratracheal direction of fungal spores induced allergic asthma in mice." (PMID 33413198, 2021). "Evidence states that IL-4, IL-5, and IL-13 drive allergic asthma, which explains the importance of these molecules as drug targets in the management of T2 high allergic asthma." (PMID 34572281, 2021). "Induced allergic asthma led to lower levels of methylation in inflammatory-related genes, comprising IL-4, IL-5, IL-13, and also global DNA methylation in their lung tissue; therefore, more Th2 cytokines were produced resulting in lung inflammation." (PMID 33781317, 2021). "OXY significantly ameliorates allergic asthma by suppressing T-cell response including down regulation of IL-4, IL-5, and IL-13 expression levels." (PMID 33946346, 2021). "Lung IL-4 signaling and M2 macrophages are key regulators of airway responses to inhaled allergens, participating in poor lung function in allergic asthma 32, 44-46." (PMID 33754034, 2021). "Cytokines released from Th2 cells like IL-5 and IL-4 stimulate IgE secretion from the B cells that play an important role in allergic asthma." (PMID 35046828, 2021). "We show that prophylactic and therapeutic dual vaccination against mouse IL-4 and IL-13 reduces key features of chronic allergic asthma in mice." (PMID 33976140, 2021). "Th2 type cytokines (e.g. interleukin (IL)-4, IL-5, and IL-13) play a major role in the pathogenesis of allergic asthma." (PMID 32600285, 2020). "This paradigm of a Th2-dependent impairment of Treg function suggests a requirement for IL-4 and its receptor signaling on Tregs in allergic asthma." (PMID 32931477, 2020). "It is known that IL-4-driven immunoglobulin class-switching to IgE plays an important role in hypersensitivity reactions including food allergies and allergic asthma." (PMID 32415285, 2020). "To investigate the role of RHAS in alleviating allergic asthma recurrence, we examined the levels of IFN-γ and IL-4 cytokines associated with airway inflammation in serum." (PMID 32509851, 2020). "Kaempferol, one of the principal constituents in S. nigra, has its therapeutic implications in the treatment of allergic asthma by inhibiting IL-4, IL-5, and IL-13 secretion." (PMID 32617136, 2020). "Th2-type cytokines such as IL-4, IL-5, and IL-13 play a vital role in the progression of the allergic asthma." (PMID 32617136, 2020). "Th2 cell initiates the immune response of allergic asthma by releasing type 2 cytokines, such as IL-4 that promotes the synthesis of IgE by B cells." (PMID 32509851, 2020).
allergic asthma (continued). "Results revealed that thymol effectively reduced the symptoms of allergic asthma through dose-dependent inhibition of IL-4, IL-5 and IL-13 production at 4, 8 and 16 mg/kg in OVA-challenged mice." (PMID 31275149, 2019). "Despite these similarities, a number of in vivo functional experiments have shown that IL-4 and IL-13 facilitate different features of allergic asthma." (PMID 31340811, 2019). "Bronchial inflammation, smooth muscle spasm, and mucus production in allergic asthma are triggered by IL-4, IL-5, and IL-13, which are released by Th2 cells." (PMID 31637021, 2019). "Controlling Th2-mediated responses (i.e., the production of IL-4, IL-5, and IL-13) can have a potential therapeutic role in allergic asthma." (PMID 31637021, 2019). "The boosted Th2 cytokine (IL-4) and IgE level was seen in this study as typical characteristic of allergic asthma." (PMID 31253164, 2019). "It is accepted that increased productions of some cytokines such as IL-4, IL-5 and IL-13 play vital roles in the inflammatory mechanism of allergic asthma." (PMID 31223464, 2019). "Cytokines such as IL-4, IL-5, and IL-13 have a close relation with the phenotype of allergic asthma." (PMID 30783201, 2019). "Previous research has shown that allergic asthma and inflammation are closely correlated with overproduction of IL-4 and decreased production of IFN-γ." (PMID 31330806, 2019). "The polarization of immune responses towards Th2 cells that it has destructive effects on lung with the secretion of IL-4 and IL-5 cytokines indicating activation of this pathway during allergic asthma." (PMID 31143692, 2019). "Following induction of allergic asthma and administration of aqueous extract of P. atlantica gum, Th2 (IL-5 and IL-4) and Th17 cytokines (IL-17) significantly decreased, which did not vary significantly among different doses of the extract." (PMID 31143692, 2019). "IL-4, a type 2 cytokine, plays a key role in the pathogenesis of allergic asthma, and IL-4 levels are a major marker of type 2 helper T cells and allergic inflammation." (PMID 30400597, 2018). "IL-4 leads to the IgE formation by B-cells and IgE-mediated mast cell activation plays a pivotal role in the pathogenies of allergic asthma." (PMID 30116273, 2018). "Allergic asthma is dominated by the IL-4 (Th2) immune response that is well known since the pioneering work of Mossman and Coffman to counter-regulate the IFN-γ dominated (Th1) immune response that controls viral and bacterial infection." (PMID 30147700, 2018). "Considering the limited number of human studies, Wang and colleagues showed in their study that IL-35 suppressed IL-4 secretion in allergic asthma patients and IL-35 level was lower than that in healthy controls." (PMID 29692871, 2018). "IL-4 or IL-13 production from iNKT cells is required for the development of allergic asthma in mouse models, while iNKT cells can produce IFN-γ, which can suppress the Th2 response and thereby prevent allergic asthma." (PMID 30210497, 2018). "Interleukin (IL)-4 is a key cytokine in the development of allergic asthma and has the ability to drive the differentiation of naive T helper type 0 (Th0) lymphocytes into Th2 lymphocytes." (PMID 29160801, 2017). "Th2 cells then mediate the allergic asthma pathway through proinflammatory cytokines—i.e., interleukins (IL)-4, IL-5, IL-9, and IL-13—leading to the production of immunoglobulin E (IgE) early in the cascade and, later, eosinophils." (PMID 29176991, 2017). "In this study, we found that PBMCs from children with allergic asthma produced and secreted higher levels of Th2-specific cytokines IL-4, higher levels of IL-9, and lower levels of Th1-specificcytokine IFN-γ compared to healthy children." (PMID 28724400, 2017).